DLG4 (discs large MAGUK scaffold protein 4)
Diseases named in the same sentence as DLG4 in open-access papers (continued):
Sharing a sentence is not in itself a finding about the gene and the disease.
autism (56 papers, 2005 to 2026). Persistent deficits in social interaction and communication and interaction as well as a markedly restricted repertoire of activity and interest as well as repetitive patterns of behavior. "Mutations of DLG4, including sequence variants and copy number variants, have been identified in patients diagnosed with schizophrenia, autism, and intellectual disability." (PMID 35204682, 2022). "The deletion or variation of Dlg4 was associated with autism." (PMID 33679870, 2020). "The only other autism-specific gene in module 2 of the WES network is DLG4, which belongs to module 6 of the larger multiplex network." (PMID 33441621, 2021). "For example, mutations of DLG4 (encoding PSD95) are associated with both SCZ and autism, and a missense mutation of DLG4 (T611I) that weakens the PSD95/SAPAP interaction could interfere with synapse development and cause ID." (PMID 35433833, 2022). "Among the genes that have not previously been defined as epilepsy genes, DLG4 is the most commonly shared gene among class 1 modules and has been implicated in autism, intellectual disability, and synaptic function." (PMID 31653223, 2019). "Also within those down-regulated gene sets contains gene PSD95 (DLG4) and GABA, which have recently been found to be associated with neurological disorders like autism by altering synaptic assembly." (PMID 27356971, 2016). "DLG4 is classed under a high confidence category with a gene score of 1 in the SFARI database and has an Evaluation of Autism Gene Link Evidence (EAGLE) score of 2.45, which suggests limited but no contradicting evidence of its role in ASD." (PMID 37543562, 2023). "Interestingly, of the autism genes positively correlated with δ-catenin, there is a significant enrichment in genes involved in dendrite morphogenesis, including PDLIM5, SHANK1, CDKL5, and DLG4." (PMID 27822498, 2016).
Anxiety (51 papers, 2012 to 2026). Intense feelings of nervousness, tension, or panic often arise in response to interpersonal stresses. "Increased repetitive behaviours, abnormal communication and social interactions, impaired motor coordination, increased stress reactivity, and anxiety-related responses were shown in Dlg4 knockout mice." (PMID 32443651, 2020). "Dlg4−/− mice display abnormalities in multiple behavior tests, including increased responses related to stress and anxiety." (PMID 32635937, 2020). "For anxiety-symptom factor, SNP rs1875673 of the DLG4 gene had effect sizes of 0.006% and 5.153% for the phenotype defined with the sum score approach and bi-factor approach, respectively." (PMID 26125156, 2015). "For example, the effect of the DLG4 gene on anxiety symptoms emerged only under the bi-factor model method." (PMID 26125156, 2015). "The unique association between the DLG4 gene and specific factor on anxiety indicates that the DLG4 potentially contributes to mental health symptoms mainly through anxiety symptoms that are not shared by other dimensions of the GHQ." (PMID 26125156, 2015).
epilepsy (36 papers, 2013 to 2026). A brain disorder characterized by episodes of abnormally increased neuronal discharge resulting in transient episodes of sensory or motor neurological dysfunction, or psychic dysfunction. "The relationship between DLG4 variants and epilepsy is particularly significant in the context of synaptopathies, where abnormal synaptic architecture and neurotransmission lead to refractory epilepsy in some cases." (PMID 39596051, 2024). "Recently, variants in DLG4 encoding PSD-95 were found to cause a neurodevelopmental disorder with a variety of clinical features including intellectual disability, developmental delay, and epilepsy." (PMID 35457207, 2022). "Identification of 45 different heterozygous DLG4 variants in 53 individuals demonstrated that a deficient PSD-95 would lead to a brain disorder characterized by ID, global DD, ASD, ADHD, epilepsy, hypotonia, and movement disorders." (PMID 35457207, 2022). "Genes most frequently shared among class 1 modules (such as DLG4, GRIN2A, PRKCB, and SNAP25) have been associated with epilepsy, synaptic function, and neuronal processes." (PMID 31653223, 2019). "DLG4-related synaptopathy is a rare brain disorder characterized by intellectual disability (ID), developmental delay (DD), autism spectrum disorder (ASD), attention deficit hyperactivity disorder (ADHD), and epilepsy, associated with pathogenic DLG4 variants." (PMID 35457207, 2022). "Module 6 is also enriched in common genes as well has some epilepsy phenotypes relative to other modules, so it can also be hypothesized that DLG4, although only labelled as an Autism 1 gene, is also associated with epilepsy." (PMID 33441621, 2021). "DLG4-related synaptopathy manifests as developmental delay, muscular hypotonia, ID, ASD, ADHD, abnormal movement (stereotypies, ataxia, and dystonia), epilepsy, ophthalmologic abnormalities, and Marfanoid habitus." (PMID 38182567, 2024). "Epilepsy has scarcely been studied with reference to DLG proteins, and mostly with reference to DLG4 (PSD-95 in mouse)." (PMID 28724449, 2017). "Finally, we use our analysis to prioritize new candidate genes for epilepsy (i.e. ANK2, CACNA1E, CACNA2D3, GRIA2, DLG4) for further validation." (PMID 33441621, 2021). "In 8 patients, one or more epilepsy genes, GRIN2A, TET3, SCN1A, SCN8A, ADGRV1, DLG4, and SLC12A5, were found, and 12 patients had no genetic mutations." (PMID 38813507, 2023).
dementia (23 papers, 2014 to 2025). Loss of intellectual abilities interfering with an individual's social and occupational functions. "Among the predicted DTs, numerous serine threonine kinases, such as DLG4 (PSD-95) and a G-protein coupled receptor, Bradykinin receptors 2, were highlighted which could be considered for the development of innovative therapeutic approaches for the treatment of dementia." (PMID 26154857, 2015).
ischemia (15 papers, 2015 to 2024). A hypoperfusion of the BLOOD through an organ or tissue caused by a PATHOLOGIC CONSTRICTION or obstruction of its BLOOD VESSELS, or an absence of BLOOD CIRCULATION. "The probability of APA events in Dlg4 was lower in ischemia 0-300 s than in later periods." (PMID 37525090, 2023).
neuroblastoma (11 papers, 2015 to 2025). Neuroblastoma (NB) is the most common solid, extracranial childhood tumor. "We observed that the green fluorescence protein (GFP), examined as a reporter, was reduced in Neuro2a (N2a) cell, a mouse neuroblastoma cell line, where Dlg4 and Fxr1 were knocked down." (PMID 36732356, 2023).
glioma (9 papers, 2018 to 2026). A benign or malignant brain and spinal cord tumor that arises from glial cells (astrocytes, oligodendrocytes, ependymal cells). "DLG4 is a post-synaptic scaffold protein, which has been implicated in glioma pathogenesis by previous bioinformatic analysis." (PMID 39602392, 2024). "DLG4 has been identified as a core biomarker Biomarkers related with clinical outcome in glioma patients through a bioinformatics approach." (PMID 36313669, 2022).
glaucoma (8 papers, 2017 to 2024). Increased pressure in the eyeball due to obstruction of the outflow of aqueous humor. "Moreover, we identified Rab5b, App, Stx16, Pikfyve, Dnaja3, Cltc and Dlg4 as key genes impacting glaucoma pathogenesis by transcription differences." (PMID 33133146, 2020). "Additionally, DLG4 (discs large MAGUK scaffold protein 4) and several proinflammatory chemokines and cytokines already known to have a role in glaucoma, e.g., C-X-C motif chemokine ligand 8 (CXCL8), tumor necrosis factor (TNF), and interleukin-6 (IL-6), were other central nodes in the network." (PMID 39458974, 2024).
Huntington disease (8 papers, 2014 to 2023). Huntington disease (HD) is a rare neurodegenerative disorder of the central nervous system characterized by unwanted choreatic movements, behavioral and psychiatric disturbances and dementia. "We also found many differentially expressed genes related to the Huntington disease (HD) pathway in both areas of the MPS II mouse model; among these, Bbc3, Bdnf, Crebbp, Dctn1, Dlg4, Gpx1, Grin1, Grin2b, Itpr1, and Pparg are up-regulated, while Dnaic2, Dnali1, Hap1, and Vdac2 are down-regulated." (PMID 28513549, 2017).
fragile X syndrome (6 papers, 2015 to 2023). A genetic syndrome caused by mutations in the FMR1 gene which is responsible for the expression of the fragile X mental retardation 1 protein. "Here we show novel UPS-related factors: the fragile X mental retardation 1 (FMR1) and Fmr1 autosomal homolog 1 (FXR1) proteins and discs large MAGUK scaffold protein 4 (Dlg4) mRNA, which are associated with Fragile X syndrome, are involved in UPS activity." (PMID 36732356, 2023).
breast carcinoma (4 papers, 2016 to 2025). "DLG4 is downregulated in human cervical cancer cell lines infected with human papillomavirus and may act as a tumor suppressor, while leucine deprivation inhibits cell proliferation and induces apoptosis in breast cancer cells." (PMID 29506475, 2018).
colorectal cancer (4 papers, 2019 to 2024). A primary or metastatic malignant neoplasm that affects the colon or rectum. "DLG4 is associated with poor prognosis for prostate cancer and colorectal cancer." (PMID 33765954, 2021).
type 2 diabetes (4 papers, 2014 to 2025). "Discs large MAGUK scaffold protein 4 (DLG4) is related to neurological disorders and type 2 diabetes; DLG4 is a new biomarker for the progression of FT1D." (PMID 33083497, 2020).
intellectual developmental disorder 62 (3 papers, 2022 to 2023). "The CMA was normal but the whole exome sequencing revealed a de novo mutation in the gene DLG4, consistent with DLG4-related synaptopathy also known as SHINE syndrome." (PMID 37386468, 2023). "SHINE syndrome is a rare neurodevelopmental disorder caused by dysfunction of the postsynaptic density protein-95 (PSD-95), encoded by the DLG4 gene." (PMID 37386468, 2023). "On Feb 26, 2020, intellectual developmental disorder 62 (OMIM 618793) caused by the DLG4 variant was registered as a new entry." (PMID 35346031, 2022). "In addition, defects in the DLG4 gene of this region are known to cause intellectual developmental disorder 62 (MIM 618793) due to haploinsufficiency." (PMID 35495136, 2022). "SHINE syndrome, also known as DLG4-related synaptopathy, is a neurodevelopmental disorder due to dysfunction of the postsynaptic density protein-95 (PSD-95), encoded by DLG4." (PMID 37386468, 2023).
mental disorder (3 papers, 2018 to 2025). A disease that has its basis in the disruption of mental process. "Dysfunction of the Dlg family has been implicated in several mental disorders: Dlg4 (also known as PSD95 or SAP90), Dlg1 (also known as SAP97), and Dlg2 (also known as PSD93 or Chapsin110)." (PMID 40360818, 2025).
anxiety disorder (2 papers, 2015 to 2023). A category of psychiatric disorders which are characterized by anxious feelings or fear often accompanied by physical symptoms associated with anxiety. "However, for better understanding of severe anxiety disorder, it could be fruitful to explore DLG4 biochemical pathways." (PMID 26125156, 2015).
attention deficit-hyperactivity disorder (2 papers, 2020 to 2022). A disorder characterized by a marked pattern of inattention and/or hyperactivity-impulsivity that is inconsistent with developmental level and clearly interferes with functioning in at least two settings (e.g. at home and at school). "DLG4 is also part of the complex DLG4-NMDA-DLGAP1, which was associated with influencing executive functions, in particular the set-shifting abilities (cognitive flexibility) in attention deficit hyperactivity disorder individuals." (PMID 36561312, 2022).
leukaemia (2 papers, 2018 to 2021). "DLG4 and leucine are negatively correlated in leukemia (r = − 0.92) but positively correlated (r = 0.78) in BPO cancers." (PMID 29506475, 2018). "These opposing correlations of DLG4-leucine and FSCN1-malic acid between leukemia and BPO suggest possible tissue-specific relationships that can be differentially targeted." (PMID 29506475, 2018).
colon adenocarcinoma (1 paper, 2025). "DLG4 was downregulated in colon adenocarcinoma patients and related to the prognosis." (PMID 40629546, 2025).
multiple sclerosis (1 paper, 2023). A progressive autoimmune disorder affecting the central nervous system resulting in demyelination. "Examples include the genes Mtor, which is a major regulator of axonal growth; Dlg4, which encodes the protein PSD95; Grin1, which encodes a critical subunit of NMDA receptors; the neurofilament light chain gene Nefl, which is being developed as a biomarker in traumatic SCI and multiple sclerosis." (PMID 37653491, 2023).
Prader-Willi syndrome (1 paper, 2014). "Moreover, SNRPN, one of the deleted genes for Prader-Willi syndrome, is also directly connected to the DLG4 gene." (PMID 24410907, 2014).
neurodegenerative disease (26 papers, 2014 to 2025). A disorder of the central nervous system characterized by gradual and progressive loss of neural tissue and neurologic function. "These include key members of the post-synaptic proteome functional, structural and regulatory components (e.g. Dlg4, Fyn, Arc, CamK2b) as well as genes with known associations with neurodegenerative disease (tau)." (PMID 27069252, 2016).
neurological disorders (22 papers, 2014 to 2024). "In the literature, DLG4 is mentioned in the context of the development of neurological disorders." (PMID 39640846, 2024).
infection (18 papers, 2014 to 2025). The state of being infected such as from the introduction of a foreign agent such as serum, vaccine, antigenic substance or organism. "For time series analysis, the DEGs of JEG-3 cells in placenta tissue after infection for 3 h, 12 h and 24 h were evaluated, which involved only 2 overlapped DEGs including DLG4 and CACNA1S." (PMID 36209057, 2022).
tumor (18 papers, 2014 to 2025). "In summary, we demonstrated the tumor-suppressing function of circ_0003215 in regulating the PPP via the circ_0003215/miR-663b/DLG4/G6PD axis." (PMID 36127319, 2022). "DLG4 has been suggested to function as a tumor suppressor and is involved in the development of HPV related cancers." (PMID 28099461, 2017). "Likewise, the regulators of cell differentiation and proliferation, VEGFA, DLG4, CDK, NRP2 and ACHE, were also found to be down-regulated in the mtDNA-depleted tumours but presented higher levels of expression in the cells." (PMID 30208958, 2018).
neurodevelopmental disorder (15 papers, 2012 to 2025). A behavioral and cognitive disorder with onset during the developmental period that involves impaired or aberrant development of intellectual, motor, or social functions. "While DLG4/PSD-95 has been extensively studied with respect to its association with neurodevelopmental disorders, the results of the present study suggest a potential role for DLG2/PSD-93 in ASD as well." (PMID 32164788, 2020). "DLG4-related synaptopathy is a neurodevelopmental disorder caused by a DLG4 variant." (PMID 38182567, 2024). "This variant has been observed de novo without confirmed parentage in multiple unrelated patients with DLG4-related neurodevelopmental disorder in the published literature." (PMID 37386468, 2023).
cancer (11 papers, 2014 to 2025). A tumor composed of atypical neoplastic, often pleomorphic cells that invade other tissues. "Changes in DRD3 levels along with GDNF, GNAL, HRH2, CAV2, and DLG4 were characteristic of G1 cancer." (PMID 34768458, 2021). "Extensive evidence suggests that lncRNAs may regulate DLG4 within cancer regulatory networks." (PMID 40629546, 2025). "In the case of G3 cancer, significant reduction in ARRB2 and DLG4 levels and overexpression of TERF2IP and SLC22A2 were observed." (PMID 34768458, 2021). "Notably, DLG4 is downregulated in CRC and is inversely correlated with cancer cell proliferation." (PMID 40629546, 2025).
psychiatric disorder (11 papers, 2009 to 2025). A disorder characterized by behavioral and/or psychological abnormalities, often accompanied by physical symptoms. "In the PPI network of these Egr targets in the DG region, the top key nodes tightly associated with distinct psychiatric disorders and addictive behaviors in previous studies included Syt1, Stx1a, Dlg4, Cplx1, Gria1, Snap25, Rab3a, and Bdnf81,86–91." (PMID 37758941, 2023).
brain disorder (9 papers, 2014 to 2023). A disease affecting the brain or part of the brain. "Until our group recently described DLG4-related synaptopathy as a novel brain disorder, the association between dysfunctional DLGs and neurodevelopmental/neuropsychiatric conditions had been scarcely defined." (PMID 35457207, 2022). "Majority of the DLG4 variants are predicted to lead to haploinsufficiency of PSD-95 resulting in a brain disorder, which suggests that the other members of the DLG subfamily are unable to compensate for PSD-95, as could have been expected." (PMID 35457207, 2022).
DLG4 also shares sentences with these, for which no sentence is quoted: memory impairment (42 papers); cognitive decline (37); Cerebral ischemia (21); ischemic stroke (20); autism spectrum disorder (14); diabetes (12); tauopathy (10); amyloid (9); Intellectual disability (9); Sepsis (9); cognitive disorder (7); Angelman syndrome (6); melanoma (6); developmental delay (5); Seizure (5); Ataxia (4); delirium (4); neuropathic pain (4); Parkinson disease (4); vascular dementia (4); astrocytoma (3); cerebral infarction (3); dementia with Lewy bodies (3); Dyskinesia (3); Hyperglycemia (3); lung carcinoma (3); mood disorder (3); Obesity (3); peripheral nerve injury (3); peripheral neuropathy (3).
A further 102 diseases each share a sentence with DLG4 in 3 papers or fewer.